KCTD13 (potassium channel tetramerization domain containing 13)
Description:
Substrate-specific adapter of a BCR (BTB-CUL3-RBX1) E3 ubiquitin-protein ligase complex required for synaptic transmission. The BCR(KCTD13) E3 ubiquitin ligase complex mediates the ubiquitination of RHOA, leading to its degradation by the proteasome Degradation of RHOA regulates the actin cytoskeleton and promotes synaptic transmission (By similarity). Mediates also the ubiquitination and degradation of GluN1/GRIN1 to regulate excitatory synaptic transmission and seizure susceptibility.
Synonyms: hBACURD1; BACURD1; PDIP1; POLDIP1; FKSG86
Tractability: PROTAC: ubiquitination databases record sites on it.
Gene: Protein-coding gene on chromosome 16 (29,905,012 to 29,926,236, reverse strand). Ensembl gene ENSG00000174943.
Subcellular location: Nucleus; Cytoplasm
Subcellular location (Human Protein Atlas): Nuclear bodies; Nucleoplasm
Pathways (Reactome):
Signal Transduction: RND2 GTPase cycle; RND3 GTPase cycle
Gene Ontology:
Molecular function: identical protein binding; protein binding; ubiquitin-like ligase-substrate adaptor activity; ubiquitin-protein transferase activity; protein domain specific binding
Biological process: cell migration; negative regulation of Rho protein signal transduction; proteasome-mediated ubiquitin-dependent protein catabolic process; protein ubiquitination; stress fiber assembly; neural precursor cell proliferation; positive regulation of synaptic transmission; positive regulation of DNA replication; protein homooligomerization; ubiquitin-dependent protein catabolic process
Cellular component: Cul3-RING ubiquitin ligase complex; nuclear body; nucleoplasm; cytosol; cytoplasm; nucleus
Genetic constraint (gnomAD): Loss-of-function variants: 15 observed, 32.39 expected, observed/expected ratio (o/e) 0.46, 90% interval 0.31 to 0.71. The upper end of that interval is the gene's LOEUF score, 0.71, which puts it in group 2 of 6, group 1 being the genes least tolerant of losing a copy. Missense variants: 337 observed, 470.81 expected, observed/expected ratio (o/e) 0.72, 90% interval 0.65 to 0.78. Synonymous variants: 189 observed, 212.7 expected, observed/expected ratio (o/e) 0.89, 90% interval 0.79 to 1.
Homologues: Orthologues: chimpanzee KCTD13 (100% identical), macaque KCTD13 (99% identical), rabbit KCTD13 (98% identical), dog KCTD13 (97% identical), pig KCTD13 (97% identical), rat Kctd13 (95% identical), mouse Kctd13 (94% identical), guinea pig KCTD13 (87% identical), zebrafish kctd13 (62% identical), Drosophila melanogaster CG10465 (54% identical), Caenorhabditis elegans D2045.8 (26% identical), Caenorhabditis elegans F22E5.11 (21% identical), and 27 more. Paralogues in human: KCTD10 (66% identical), TNFAIP1 (63% identical).
Diseases named in the same sentence as KCTD13 in open-access papers:
KCTD13 is named in the same sentence as 29 diseases in open-access papers, as found by Europe PMC text mining. Sharing a sentence is not in itself a finding about the gene and the disease. The quoted sentences say what the papers report.
microcephaly (11 papers, 2013 to 2023). A congenital or acquired developmental disorder in which the circumference of the head is smaller than normal for the person's age and sex. "In a zebrafish model, potassium channel tetramerization domain-containing 13 (KCTD13) was identified as the sole signaling protein capable of inducing the microcephaly phenotype associated with 16p11.2 duplication." (PMID 37958606, 2023). "In zebrafish, the suppression of potassium channel tetramerization domain containing 13 (KCTD13) was associated with macrocephaly whereas overexpression led to microcephaly." (PMID 30443311, 2018). "In addition, gene copy number variants (CNVs) of KCTD13 mapping to chromosomal location 16p11.2 are considered to be major genetic causes of macrocephaly and microcephaly." (PMID 24268103, 2013). "KCTD13 is found in the 16p11.2 chromosomal interval, where deletions are associated with macrocephaly, ASD and ID, and duplications with microcephaly, ASD and schizophrenia." (PMID 30210288, 2018). "Overexpression of KCTD13 induces microcephaly, whereas suppression of the same locus results in a macrocephalic phenotype." (PMID 24268103, 2013).
autism (6 papers, 2019 to 2024). Persistent deficits in social interaction and communication and interaction as well as a markedly restricted repertoire of activity and interest as well as repetitive patterns of behavior. "On the other hand, deletion of copy number of KCTD13 was also linked to other conditions like epilepsy and autism." (PMID 39318621, 2024). "Autism and schizophrenia have been associated with KCTD13 deletions, and obesity was associated with KCTD15 variants." (PMID 39202342, 2024). "KCTD13 modulates synaptic transmission by suppressing RHOA signalling via interaction with the ubiquitin ligase CUL3, itself an autism risk factor." (PMID 36658491, 2023). "Varying levels of evidence support their roles in neurocognitive disorders (KCTD3), neurodevelopmental disease (KCTD7), bipolar disorder (KCTD12), autism and schizophrenia (KCTD13), movement disorders (KCTD17), cancer (KCTD11), and obesity (KCTD15)." (PMID 31197948, 2019). "Our predictions highlight the peculiar oligomerization properties of the members of Cluster 6 (KCTD10, KCTD13, and TNFAIP1), which are involved in important neurological pathologies including autism." (PMID 36362127, 2022).
schizophrenia (5 papers, 2019 to 2025). A major psychotic disorder characterized by abnormalities in the perception or expression of reality. "For example, 17.2% of genetic variation in schizophrenia in the KCTD13 locus is explained by the expression of genes in blood tissue, 75.2% in the cerebellum, and 59.4% in the cortex." (PMID 40270926, 2025). "While most associations we detected were in the expected direction given previous knowledge, MVP and KCTD13 were associated with BMI in the opposite (positive) direction, and YPEL3 with schizophrenia in the negative direction." (PMID 34715901, 2021).
autism spectrum disorder (4 papers, 2019 to 2025). A spectrum of developmental disorders that includes autism, and Asperger syndrome. "Recent analysis of a novel Kctd13 null mutant, which lies within the 16p11.2 region associated with autism spectrum disorder and disability uncovered a range of cognitive phenotypes similar to mouse deletion mutants covering the homologous region." (PMID 34089057, 2021).
hypospadias (3 papers, 2024 to 2025). Hypospadias is the displacement of the urethral meatus on the ventrum of the penis. "Further analysis showed that KCTD13 CNV deletion was still significantly associated with more severe hypospadias after adjustment for BMI by logistic regression model." (PMID 39318621, 2024). "Frequency distributions of KCTD13 CNV among different severity of hypospadias and its association with severity levels." (PMID 39318621, 2024). "Additionally, further research is still required to elucidate the molecular mechanisms underlying the association between KCTD13 and hypospadias." (PMID 39318621, 2024). "It indicated that patients with KCTD13 CNV deletion have a significantly increased risk for proximal hypospadias (OR = 10.07, 95% CI = 2.91–34.84, P = 2.70 × 10−4) and midshaft hypospadias (OR = 6.08, 95% CI = 1.69–21.84, P = 0.006) compared to the distal hypospadias." (PMID 39318621, 2024). "However, our study did not identify any significant associations between SPL or glans width and KCTD13 CNV among isolated cases of hypospadias in children aged 1–3 years old." (PMID 39318621, 2024). "However, due to the limited sample size of hypospadias cases in this study, the association between KCTD13 CNV and isolated hypospadias remains unclear." (PMID 39318621, 2024). "KCTD13 (potassium-channel-tetramerization-domain-containing-13) is another candidate gene potentially involved in cryptorchidism and hypospadias." (PMID 41595460, 2025). "Our findings further validated these previous results and suggested that children with isolated hypospadias are more likely to exhibit KCTD13 copy number deletion." (PMID 39318621, 2024). "Incidence of KCTD13 CNV deletion was significantly increased with the severity of hypospadias, P_trend = 9.00 × 10−6." (PMID 39318621, 2024). "Previous research showed that a patient presenting both hypospadias and cryptorchidism exhibited KCTD13 copy number duplications, whereas only one case with isolated hypospadias displayed KCTD13 copy number deletion." (PMID 39318621, 2024). "In our study, all the determinations of KCTD13 CNV type in isolated hypospadias patients were deletion." (PMID 39318621, 2024). "In conclusion, our study provides substantial evidence of an association between KCTD13 CNV deletion and susceptibility to isolated hypospadias." (PMID 39318621, 2024). "Our study determined the presence of KCTD13 CNV in cases of hypospadias and contributed to the evidence, indicating that the deletion of CNV in KCTD13 was significantly associated with increased risk to isolated hypospadias in a Chinese population." (PMID 39318621, 2024). "Comparison of general characteristics and clinical data of KCTD13 CNV status among hypospadias patients." (PMID 39318621, 2024). "And for the first time, we have demonstrated the high prevalence of KCTD13 CNV among Chinese children with isolated hypospadias." (PMID 39318621, 2024). "However, there is lack of population-level evidence to assess the contribution of KCTD13 CNV to hypospadias." (PMID 39318621, 2024). "CNV in KCTD13 has been identified to influence androgen receptor function via its changes in gene dosage, which might contribute to hypospadias." (PMID 39318621, 2024). "Therefore, we hypothesize that KCTD13 CNV may be identified in hypospadias in the Chinese population and could be associated with severity of hypospadias." (PMID 39318621, 2024). "Furthermore, the prospective clinical utilization of KCTD13 copy number deletion may aid in evaluating and predicting the long-term development of masculinization in children with varying degrees of hypospadias, especially those with proximal hypospadias." (PMID 39318621, 2024). "However, the precise role of KCTD13 CNV in hypospadias remains to be clarified." (PMID 39318621, 2024).
hypospadias (continued). "Patients with distal, midshaft, and proximal isolated hypospadias all exhibited a certain proportion of KCTD13 CNV, and the prevalence of KCTD13 copy number deletion increased as the severity of hypospadias worsened (P < 0.001)." (PMID 39318621, 2024). "In addition, the association between genital characteristics (stretched penile length and glans width) and KCTD13 CNV showed no significance in hypospadias children (P > 0.05)." (PMID 39318621, 2024).
Macrocephaly (3 papers, 2022 to 2024). Occipitofrontal (head) circumference greater than 97th centile compared to appropriate, age matched, sex-matched normal standards. "The KCTD13 gene is a key driver of neuronal proliferation in zebrafish and mice and a major driver of the 16p11.2 microdeletion syndrome macrocephaly, and MAPK3 and MVP genes in the deletion region may act as modifier genes to enhance the expression of KCTD13 gene." (PMID 36553582, 2022).
Anxiety (2 papers, 2020 to 2025). Intense feelings of nervousness, tension, or panic often arise in response to interpersonal stresses. "With regard to anxiety, Kctd13 and Taok2 loss of function in mice promoted anxiety‐like behaviors." (PMID 39988938, 2025).
Cognitive impairment (2 papers, 2021 to 2023). Abnormal cognition is characterized by deficits in thinking, reasoning, or remembering. "Similarly, in the social domain, the contribution of each gene within the deleted region could also be detailed, as it has been done to identify the contribution of Kctd13 gene to the cognitive impairment phenotype." (PMID 38173978, 2023).
cryptorchidism (2 papers, 2024 to 2025). The failure of one or both testes of a male fetus to descend from the abdomen into the scrotum during the late part of pregnancy. "In mice, KCTD13 haploinsufficiency causes an increased incidence of cryptorchidism." (PMID 41595460, 2025). "In the same way, in vivo KCTD13-null mice exhibited reduced nuclear AR levels, decreased expression of SOX9, smaller testis, cryptorchidism, micropenis, and subfertility." (PMID 41595460, 2025).
Alzheimer disease (1 paper, 2025). A progressive, neurodegenerative disease characterized by loss of function and death of nerve cells in several areas of the brain leading to loss of cognitive function such as memory and language. "In this study, we identified known ADRD loci located in SHARPIN and TNIP1, along with nine novel risk loci − including KCTD13 – that are shared between Alzheimer’s disease and hippocampal volume." (PMID 40787599, 2025).
Macrosomia (1 paper, 2023). "Macrosomia may be prevalent in microdeletion cases, while macrosomia is common in microduplication cases, probably due to differential KCTD13 expression." (PMID 37013606, 2023).
psychiatric disease (1 paper, 2016). "Significantly, a recent study implicated a KCTD13-Cul3-RhoA signalling pathway to be important for human nervous system development and psychiatric disease." (PMID 26969432, 2016).
tumor (1 paper, 2021). "In this study, we systematically assessed the prognostic performance of DNA replication-related genes for predicting tumor recurrence and constructed a novel and robust signature including EREG, KCTD13, MCM3AP, MCM3, POLD2, TERF2, and TP73." (PMID 33748108, 2021).
KCTD13 also shares sentences with these, for which no sentence is quoted: epilepsy (4 papers); Intellectual disability (3); Obesity (2); bipolar disorder (1); breast carcinoma (1); breast tumors (1); cancer (1); dementia (1); Micropenis (1); movement disorder (1); neurodegenerative disease (1); neurodevelopmental disorder (1); Parkinson disease (1); PHACE syndrome (1); psychosis (1); spondylocostal dysostosis (1).